ARG1 (arginase 1)
Diseases named in the same sentence as ARG1 in open-access papers (continued):
Sharing a sentence is not in itself a finding about the gene and the disease.
tumor (continued). "Similar as observed for human disease, MDSC showed a pathologic activation with enhanced levels of arginase-1 and PD-L1, high T cell suppressive capacity, and compartmentalized differences accentuating tumor-resident MDSC with increased suppressive activity." (PMID 31694706, 2019). "Consumption of l-arginine (Arg) by arginase 1 (ARG1) represents a well-known immunoregulatory mechanism exploited by M2 macrophages and myeloid-derived suppressor cells (MDSCs) in tumor settings." (PMID 31354721, 2019). "In turn, the lactate-induced expression of arginase 1 by macrophages also plays an important role in tumor growth." (PMID 31998650, 2019). "As our data revealed, ARG1 was significantly downregulated in HCC, and the higher expression of ARG1 was positively correlated with more aggressive tumor growth, size, ALT, and GGT level." (PMID 30320132, 2018). "M0 macrophages differentiated from BMDMs prominently showed Arg1+ M2 polarization in coculture with radiation-EndMT-derived tumour ECs." (PMID 30504836, 2018). "We also used a specific siRNA to inhibit the expression of RUNXOR and then detected the Arg1 level in MDSCs from tumor tissue." (PMID 29914443, 2018). "Arg1 is an M2 marker and its expression was increased in spleen CD11b+ cells of Shb knockout mice with tumors compared with non-tumor bearing mice." (PMID 29721156, 2018). "We also assessed gene expression of various factors associated with the suppressive function of MDSCs including S100A8, S100A9, Nos3, Arg1 and Arg2 in BM-MDSCs compared to G-MDSCs from the tumor, spleen and lungs of tumor-bearing mice." (PMID 29677215, 2018). "Namely, tumor-associated ECs express and release IL-6, jointing with CSF-1 in the microenvironment, induces HIF-2α-dependent arginase-1 expression through activation of PPAR-γ, leading to macrophage alternative polarization and GBM progression." (PMID 29422647, 2018). "Accumulation of MDSCs was reported during tumor progression in NB mouse models and promoted in vivo tumor growth through production of ROS, ARG-1, and TGF-β." (PMID 29682521, 2018). "Among those factors it has been previously demonstrated that CD11b+/Cd45-microglial cells are located around the tumor and express arginase-1 (ARG-1), which in turn stimulates the tumor proliferation." (PMID 30123112, 2018). "Although arginase 1 (Arg1) and Vegf increased, the expression of most prototypically protumor genes we evaluated was decreased in cells from tumor-bearing mice (left), with a concomitant increase in all proinflammatory genes evaluated (right)." (PMID 29920191, 2018). "The importance of arginase-1 in tumor development was demonstrated by the use of arginase-1 KO mice, which presented tumors 50% smaller than tumors from wild type mice." (PMID 29629338, 2018). "Cancer cell-secreted lactate from glycolysis was shown to stabilize HIF in tumor-associated macrophages (TAMs) leading to induction in VEGF and arginase 1 (ARG1), markers associated with an M2 phenotype." (PMID 29896451, 2018). "These macrophages produce ARG1, a metabolic enzyme that generates polyamines (metabolites essential for cell division), which promote tumour growth in this context." (PMID 29725601, 2018). "Tumor-MDSC highly express the enzyme arginase-1 (ARG1) which catabolizes l-arginine to urea and ornithine, thereby inhibiting T-cell proliferation through decreased CD3-theta chain expression." (PMID 30298121, 2018). "Inhibitors like nor-N-hydroxy-L-arginine and aminoguanidin (or 1400W) downregulate ARG-1 and iNOS activity in MDSCs, restore T cell antitumor immunity and reduce tumor progression." (PMID 30233579, 2018). "HPH-15 administration significantly reduced these subsets as well as the expression of Arg1 and Ym1 mRNAs, established markers of M2 macrophages, in the skin lesions of bleomycin-treated mice." (PMID 29544542, 2018).
tumor (continued). "Analyses of the tumor tissue extracts showed that the levels of phosphorylated Src and Arg-1 were remarkably higher in tumors derived from NIH-3T3/Src cells mixed with M2 macrophages as compared to NIH-3T3/Src cells alone." (PMID 29707119, 2018). "Significant expression of human Arg-1 was detected in the tumor-infiltrating human monocytes/macrophages, whereas monocytes/macrophages in the spleen and PB showed modest expression." (PMID 29456539, 2018). "Arg‐1 in tumour macrophages or co‐cultured macrophages further increased following irradiation of the tumour or radiation of the tumour cells used in co‐culture, respectively." (PMID 30442705, 2018). "In vivo PDE5 inhibition reduced ARG1 and NOS2 and down-regulated IL-4Rα in tumour-associated MDSCs in BALB/c and C57BL/6 tumour-bearing mice." (PMID 29743944, 2018). "Other substances released from N2 TANs, such as reactive oxygen species (ROS), Arginase 1 (ARG1), also contributed to enhance tumor progression." (PMID 29930287, 2018). "At the same time, Arg1 activity and ROS production were also reduced in MDSCs sorted from tumor tissues and spleen when HOXA1 was overexpressed." (PMID 29662483, 2018). "On the third week, MDSCs from tumor tissues and spleen were isolated, and Arg1 activity and ROS production in MDSCs were measured." (PMID 29662483, 2018). "The results showed that IL-1β and IL-12 expression levels were increased in the Ndrg2−/− group together with a decrease in Arg-1 expression levels, revealing a tumor-suppressor phenotype." (PMID 29445150, 2018). "Regardingthe immunohistochemical markers, the tumor was focally positive for pancytokeratin,Hep-Par-1, and arginase-1 (Arg-1), consistent with hepatoid differentiation." (PMID 30241223, 2018). "Arg‐1 was present at high baseline levels in TAMs and BMDMs co‐cultured with tumour cells, suggesting that the tumour cells themselves help condition the macrophages towards an immunosuppressive phenotype." (PMID 30442705, 2018). "Pegzilarginase is a bioengineered human PEGylated arginase 1 with enhanced pharmacological properties that displays single-agent anti-tumor activity in a number of preclinical solid tumor models and clinical activity in dose escalation studies." (PMID 30400835, 2018). "Macrophage Arg1 expression also enhances tumor-cell growth and suppresses tumor cytotoxicity by inhibiting NO production." (PMID 30619850, 2018). "In cancer development, MDSCs accelerate tumor progression by inhibiting the T cell response and inducing regulatory T cells by releasing arginase 1 (Arg1), reactive oxygen species (ROS), and inducible nitric oxide synthase." (PMID 29662483, 2018). "Arginase-1 is an enzyme expressed by immune inhibitory cells, such as myeloid derived suppressor cells (MDSCs), that reduces arginine availability to the tumor infiltrating immune cells and thus reduces T cell functionality in the tumor milieu." (PMID 30400835, 2018). "In summary, for the first time, we shed light on the fact that ARG1 is downregulated in HCC tumor and correlated with prognosis of HCC patients." (PMID 30320132, 2018). "PDE-5-i were shown to reverse MDSC function in cancer patients and augment anti-tumor immunity by inhibiting the degradation of cyclic guanosine monophosphate (cGMP), leading to reduction in ARG1 and iNOS expression." (PMID 30298121, 2018). "Neutrophils are stimulated to release immunosuppressive arginase 1 by supernatants from tumor cells in a CXCL8-dependent manner, and knockdown of CXCL8 blocks this effect." (PMID 30619286, 2018). "Here we use CB-1158, a potent and orally-bioavailable small-molecule inhibitor of arginase, to investigate the role of Arg1 in regulating anti-tumor immunity." (PMID 29254508, 2017). "Secondly, genetic ablation of Arg1 in the myeloid compartment of tumor-bearing mice was shown to reduce tumor growth, indicative of a pro-tumorigenic and immune suppressive role for Arg1 in vivo." (PMID 29254508, 2017).
tumor (continued). "While Vegf induces angiogenesis, ARG-1 contributes to tumor growth by the generation of polyamines which act as a proliferative signal for mammalian cancer cells." (PMID 28360914, 2017). "The present study additionally demonstrates that Arg1 inhibition with CB-1158 raises tumor and plasma arginine and increases inflammation in the TME." (PMID 29254508, 2017). "In analogy to M1/M2 polarization in macrophages, MDSCs exhibit M2 characteristics, which promotes tumor growth by enhancing ARG-1 activity." (PMID 28002798, 2017). "We observed that macrophages differentiated with CM polarized toward an anti-inflammatory, tumor-tolerant phenotype showing increased expression of Arginase 1, Ccl2, and Vegf." (PMID 29167669, 2017). "Recently it has been shown that lactic acid, a byproduct of anaerobic glycolysis in tumor cells under hypoxic conditions, induces the gene expression of Vegf and Arg-1 in TAM." (PMID 28471401, 2017). "Our in vitro data shows that PN1a-secreted factors can induce macrophages to express a unique set of cytokines, including Arg1 and Tgfb, which have been shown to suppress tumor cell proliferation and CD8+ T-cell activity." (PMID 28881599, 2017). "In fact, immunohistochemical analysis revealed that many M2 macrophages (arginase 1-positive macrophages) infiltrated not only primary tumor tissues but also metastatic liver lesions in CRC." (PMID 29108252, 2017). "We observed in our 3D co-culture model that tumor/fibroblast spheroids induced an M2 polarization of co-cultured monocytes with a CD14+ CD163+ HLA-DRlow CD86low ARG-1+ phenotype which resembles the phenotype of TAMs in PDAC." (PMID 28750018, 2017). "In a non orthotopic syngeneic tumour model, arginase 1 activity was significantly correlated with tumour volumes (reaching up to 4 ml) in wildtype mice." (PMID 28250926, 2017). "We found an abundance of Arg1+ infiltrating immune cells in multiple tumor types, with especially high numbers in tumors of the lung, gastrointestinal tract, and bladder." (PMID 29254508, 2017). "Patient tumor samples from multiple histologies expressed an abundance of tumor-infiltrating Arg1+ myeloid cells." (PMID 29254508, 2017). "Tumour-resident DCs exhibited pronounced upregulation of Mapkapk2 by 1.9-fold as compared to splenic DCs and also expressed high levels of Il10, Tgfb1 and Arg1, suggesting robust immunosuppressive activity of these cells within the TME." (PMID 28924177, 2017). "TAMs from human neoplasms express arginase 1, interleukin (IL)-10, and transforming growth factor beta (TGF-β); these cytokines reduce the antitumor activity of T cells and natural killer cells, and modulate tumor proliferation, infiltration, and angiogenesis." (PMID 28415741, 2017). "Consistent with increased Arg1 levels, Arg1 enzymatic activity was increased as well in MDSCs isolated from B16 tumor bearing CebpaΔ/Δ mice compared to controls." (PMID 29070836, 2017). "To explore the in vivo relevance of above findings, we analyzed the correlation of IL-33 expression with Ki-67 proliferation index (PI), and expressions of arginase 1, IL-10 and FoxP3 in tumor tissues of NSCLC patients." (PMID 28978138, 2017). "TIMs also secrete arginase 1 in the tumour microenvironment, reducing L-arginine in situ and inhibiting CTL production and function." (PMID 28913366, 2017). "Human tumor tissue microarrays were probed for Arg1 expression by immunohistochemistry and immunofluorescence." (PMID 29254508, 2017). "l-Arginine depletion by enzymatic activity of Arg-1 is probably one of the most important mechanisms employed by MDSCs to mediate local immune suppression in the tumor." (PMID 28220123, 2017). "A survey of human tumor microarrays and cancer patient plasma confirmed Arg1 expression is elevated in human cancer." (PMID 29254508, 2017). "Naturally the N1-protumor phenotype secretes more immunoactive cytokines, expresses lower levels of Arg-1, and possesses greater ability to kill tumor cells." (PMID 28220123, 2017).
tumor (continued). "Together, these results provide evidence that Arg1 activity promotes tumor growth and that elimination of myeloid cell Arg1 expression or pharmacological blockade of arginase by CB-1158 limits tumor growth in vivo." (PMID 29254508, 2017). "Evaluation of human tumor specimen also confirmed Arg1 expression in both TAMs and other myeloid-derived cells such as neutrophils." (PMID 27936099, 2016). "Intriguingly, classical M2 markers including Cd206 (Mrc1), Cd163, Pdl2 (Pdcd1lg2), Ccr3, Arg1 and many others were all markedly downregulated in TAMs isolated from the St2−/− background as compared with those isolated from tumours grown in wt mice." (PMID 27150562, 2016). "Unlike in naïve SHIP−/− mice or SHIP−/− mice with 67NR tumors, 4T1 tumor-bearing SHIP−/− mice possessed MDSCs that expressed Arg1 and were over 40-fold more immunosuppressive on a per cell basis than MDSCs isolated from 4T1 tumor-bearing WT mice." (PMID 26683227, 2016). "MDSCs affect anti-tumor immune responses by numerous mechanisms including strong activation of iNOS and Arg-1, leading to an intensive NO production and deprivation of amino acid L-arginine." (PMID 27256519, 2016). "ARG1 is expressed in myeloid cells, including TAMs, and can support tumor growth and suppresses antitumor immune responses." (PMID 26909082, 2016). "Similar to peripheral blood, we found significant accumulation of tumor-infiltrating myeloid cells compared to adjacent NT, which were primarily granulocytic and expressed ARG1." (PMID 28008330, 2016). "Expression of Arg1 by these cells at later stages of tumor growth also suggest their role in suppressing the immune response at the tumor edge." (PMID 27936099, 2016). "We also confirmed that the arginase-1 in spleen and tumor tissue were reduced by gemcitabine and aspirin." (PMID 26879926, 2016). "In contrast, tumor MG (i.e. CD11b+/CD45low cells) were typically located around tumor edge and expressed Arg1 later during tumor progression." (PMID 27936099, 2016). "Immunohistochemical assessment for Arg1 expression also highlighted numerous tumor-infiltrating leukocytes of predominant neutrophilic lineage." (PMID 27936099, 2016). "TAMs showed a M2-like phenotype characterized by expression of Cd206 (Mrc1), Cd163, Pdl2 (Pdcd1lg2), Chi3i3, Arg1, as well as tumour-promoting molecules involved in invasion and metastasis like MMPs." (PMID 27150562, 2016). "Because Arg1 was upregulated in both tumor MG and MPs, we next analyzed the expression of other associated genes in this pathway." (PMID 27936099, 2016). "A genome-wide microarray expression analysis demonstrated significant upregulation of Arg1 in both tumor MG and MPs as compared to circulating monocytes." (PMID 27936099, 2016). "We examined both intra-tumor macrophage (F4/80+) localization and the extent of M2 (i.e., Arginase 1 positive (Arg1+)) polarization in these macrophages." (PMID 27825136, 2016). "In order to evaluate the contribution of each cell type to tumor immunosuppression through Arg1 expression at the initial stages of tumor growth, chimeric mice were generated prior to tumor implantation." (PMID 27936099, 2016). "Because most Arg1+ cells were located within tumor mass, it is possible that a significant contributor to the local tumor immunosuppression can be alleviated through tumor debulking." (PMID 27936099, 2016). "In summary, these findings suggested that secretion of tumor factors resulted in migration of Arg1+ cells from the blood and upregulation of Arg1 expression by local CNS MG." (PMID 27936099, 2016). "Nevertheless, the expression of M2a markers (that is, CD163 (Cd163), mannose receptor complex-1 (Mrc1) and arginase-1 (Arg1) was significantly upregulated in sST2 low-expressing tumours." (PMID 27882929, 2016). "In small tumors, resident CNS MG accounted for a small fraction of Arg1-expressing cells, however, as tumor progressed, the proportion of Arg1+ MG increased." (PMID 27936099, 2016).
tumor (continued). "Increased Arg1 activity in the tumor microenvironment by myeloid cells can therefore lead to tumor immune evasion." (PMID 28536374, 2016). "M2 TAMs have a high capacity to suppress T cell proliferation by several mechanisms, including high expression of arginase-1 (Arg-1) which acts to deplete L-arginine in the tumor." (PMID 26673090, 2015). "Previous studies have shown that tumor associated macrophages express a wide range of molecules, such as TGF-β, arginase-1, EGF, VEGF and IL-10." (PMID 26509874, 2015). "In the tumor microenvironment, HIF-1α expression in tumor-associated macrophages suppresses T cell responses and induces expression of arginase 1; HIF-1α also enhances the inhibitory effect of MDSC." (PMID 26046638, 2015). "The high Arg-1 macrophage expression in the tumor microenvironment was highly reproducible using this system." (PMID 26462177, 2015). "TAMs in the postirradiated tumor microenvironment express higher levels of Arg-1, COX-2, and iNOS and promote early tumor growth in vivo." (PMID 26599017, 2015). "We compared Cox-2, Arg-1, and Ki67 mRNA expression in tumor MDSCs in OVA immunized versus PBS-treated HDC−/− mice." (PMID 26429861, 2015). "Lactic acid production by tumour cells, generated as a consequence of glucose metabolism, has been shown to be central for the signalling that induces M2-macrophages (as measured by Arg-1 expression) and vascular endothelial growth factor expression." (PMID 26174804, 2015). "Several genes that are implicated in angiogenesis (Vegfa, Hgf), suppression of immunity (Arg1, Tgfb3), and tumor invasion (Mmp2, Mmp14, Ctgf) were also highly expressed in our GAMs data set." (PMID 25658639, 2015). "Consistent data highlight the role of macrophage-derived-HIF1α in generating a localized immune privileged site within the tumor milieu via iNOS and ARG1 induction." (PMID 24605112, 2014). "MDSC exert their suppressive function by depleting l-arginine from the tumor micro-environment via the production of arginase-1." (PMID 24658839, 2014). "Granulocytic MDSCs in the spleen produce high levels of ROS via NOX2, whereas up-regulated ARG1 and iNOS in tumor-infiltrating MDSCs was reported to be critical for their suppressive function." (PMID 25514597, 2014). "Future studies need to directly examine the role of arginase-1 production by TAMs, concomitant tumor immunity and the anti-tumorigenic effect of E1A." (PMID 24614600, 2014). "Our observation of an accrual of Tie2+Arg1+ cells at the invasive front of tumor-bearing mice treated anti-VEGF agents further supported an association between TEMs and invasiveness upon anti-VEGF therapy." (PMID 24809734, 2014). "In contrast, E1A expression in MCA-205 cells inhibits arginase-1 expression by TAMs allowing for an effective local anti-tumor immune response." (PMID 24614600, 2014). "It is well established that the mechanism by which MDSC suppress T cell cytotoxicity in the tumor microenvironment is mediated by the production of L-arginine via arginase-1 and the release of iNOS." (PMID 24982761, 2014). "One major mechanism whereby TAMs suppress anti-tumor immune responses is through the production of arginase-1." (PMID 24614600, 2014). "We found that CD8 T cells which had infiltrated MCA-205-OVA tumors had significantly lower surface CD3ε than CD8 T cells from the spleen of MCA-205-OVA tumor bearing mice, a finding that is consistent with high arginase-1 activity." (PMID 24614600, 2014). "Surprisingly, Tg-induced up-regulation of ARG1, Nox2, and iNOS in tumor-infiltrating MDSCs was significantly inhibited by 4-PBA treatment." (PMID 25514597, 2014). "Acceleration of tumor growth by ER stress was mediated by modulating the levels of ARG1 and iNOS in tumor-infiltrating MDSCs, which enhanced their immunosuppressive function." (PMID 25514597, 2014). "Among the population of CD16/32LO tumor infiltrating cells, transcripts of the neutrophil granule protein arginase 1 were markedly elevated." (PMID 24416335, 2014).